MYO1E (myosin IE)
Description:
Actin-based motor molecule with ATPase activity. Unconventional myosins serve in intracellular movements. Their highly divergent tails bind to membranous compartments, which are then moved relative to actin filaments. Binds to membranes containing anionic phospholipids via its tail domain. Involved in clathrin-mediated endocytosis and intracellular movement of clathrin-coated vesicles. Required for normal morphology of the glomerular basement membrane, normal development of foot processes by kidney podocytes and normal kidney function. In dendritic cells, may control the movement of class II-containing cytoplasmic vesicles along the actin cytoskeleton by connecting them with the actin network via ARL14EP and ARL14.
Synonyms: MYO1C; HuncM-IC; MGC104638; FSGS6
Tractability: Antibody: its Gene Ontology location is reachable by antibodies, with medium confidence; the Human Protein Atlas places it where antibodies can reach. PROTAC: ubiquitination databases record sites on it; its protein half-life has been measured.
Gene: Protein-coding gene on chromosome 15 (59,132,434 to 59,372,871, reverse strand). Ensembl gene ENSG00000157483.
Subcellular location: Cytoplasm; Cytoplasm, cytoskeleton; Cytoplasmic vesicle; Cytoplasmic vesicle, clathrin- coated vesicle; Cell junction
Subcellular location (Human Protein Atlas): Nucleoplasm; Plasma membrane; Cytosol
Gene Ontology:
Molecular function: actin filament binding; ATP hydrolysis activity; calmodulin binding; phosphatidylinositol binding; protein binding; ATP binding; cytoskeletal motor activity
Biological process: endocytosis; glomerular basement membrane development; glomerular filtration; glomerulus development; podocyte development
Cellular component: anchoring junction; clathrin-coated endocytic vesicle; cytoskeleton; extracellular exosome; actin cytoskeleton; adherens junction; cytoplasm; cytoplasmic vesicle; microvillus; myosin complex; plasma membrane; brush border; clathrin-coated vesicle
Genetic constraint (gnomAD): Loss-of-function variants: 64 observed, 141.38 expected, observed/expected ratio (o/e) 0.45, 90% interval 0.37 to 0.56. The upper end of that interval is the gene's LOEUF score, 0.56, which puts it in group 2 of 6, group 1 being the genes least tolerant of losing a copy. Missense variants: 1,293 observed, 1,365.4 expected, observed/expected ratio (o/e) 0.95, 90% interval 0.9 to 0.99. Synonymous variants: 573 observed, 503.35 expected, observed/expected ratio (o/e) 1.14, 90% interval 1.06 to 1.22.
Homologues: Orthologues: chimpanzee MYO1E (99% identical), macaque MYO1E (98% identical), dog MYO1E (98% identical), rabbit MYO1E (97% identical), pig MYO1E (97% identical), mouse Myo1e (96% identical), guinea pig MYO1E (96% identical), rat Myo1e (96% identical), tropical clawed frog myo1e (86% identical), zebrafish myo1ea (82% identical), Caenorhabditis elegans hum-1 (57% identical). Paralogues in human: MYO1F (72% identical), MYH7 (34% identical), MYH6 (33% identical), MYH2 (32% identical), MYH8 (32% identical), MYH1 (32% identical), MYH13 (32% identical), MYH3 (32% identical), MYH4 (32% identical), MYH7B (32% identical), MYH10 (31% identical), MYO7A (31% identical), and 32 more.
Diseases named in the same sentence as MYO1E in open-access papers:
MYO1E is named in the same sentence as 48 diseases in open-access papers, as found by Europe PMC text mining. Sharing a sentence is not in itself a finding about the gene and the disease. The quoted sentences say what the papers report.
breast carcinoma (9 papers, 2016 to 2025). "In agreement with our findings, meta-analysis of patient survival data indicated that MYO1E expression level was associated with reduced recurrence-free survival in basal-like breast cancer." (PMID 27329840, 2016). "High MYO1E expression level in basal breast cancer and grade 1 breast cancer was associated with decreased patient survival, indicating that MYO1E could serve as a biomarker predicting cancer progression and overall patient outcome." (PMID 27329840, 2016). "An increase of MYO1E expression was found as a gene signature in patients with poor outcome in basal-like breast cancer (BLBC)." (PMID 32272642, 2020). "Using the MMTV-PyMT murine model of breast cancer, we identified Myosin 1e (MYO1E) as a novel tumor promoter." (PMID 27329840, 2016). "Based on the identification of MYO1E as a component of the gene signature for basal-like breast cancer, we set out to use the MYO1E KO mice and the MMTV-PyMT model of breast cancer to determine how the loss of MYO1E affects tumor progression." (PMID 27329840, 2016). "Using the well-characterized MMTV-PyMT model of breast cancer, we identify MYO1E as an important contributor to malignancy, regulating tumor progression and metastasis." (PMID 27329840, 2016). "Our data provide strong evidence for MYO1E function in breast cancer progression and contribution to tumor malignancy through regulation of cell proliferation and differentiation." (PMID 27329840, 2016). "Meta-analysis of human patient data showed a correlation between high MYO1E expression and decreased patient survival in both basal-like and grade 1 breast cancer." (PMID 27329840, 2016). "To characterize the role of MYO1E in tumor formation and progression, we crossed MYO1E KO mice with the well-characterized MMTV-PyMT mouse model of breast cancer." (PMID 27329840, 2016). "Interestingly, as the entire myosin superfamily, its internal members have different roles in tumors; for example, MYO1A can inhibit gastrointestinal tumors, while MYO1E can promote breast cancer invasion." (PMID 34322156, 2021). "The role of MYO1E in breast cancer has become more evident in recent years." (PMID 32272642, 2020). "Based on our data, we hypothesize that MYO1E is an important regulator of breast cancer tumorigenesis, promoting tumor progression." (PMID 27329840, 2016). "Finally, MYO1E upregulation has been identified as part of the gene signature that predicts poor patient outcome in basal-like breast cancer, suggesting that MYO1E promotes tumorigenesis." (PMID 27329840, 2016). "In order to determine how MYO1E expression relates to patient outcome in breast cancer, we performed a meta-analysis of patient survival using KM Plotter and found that high MYO1E expression correlated with poor patient outcome in cases of basal-like breast cancer." (PMID 27329840, 2016). "Indeed, increased MYO1E gene expression was identified as part of the gene signature that correlated with poor prognosis in patients with basal-like breast cancer." (PMID 27329840, 2016). "Finally, together with other genes, high expression of Myo1e correlates with poor prognosis of Basal Like Breast Cancer patients, since Myo1e is a key component of invadosomes a possibility is that Myo1e acts as a tumor promoter and a marker of invasive tumors." (PMID 34974807, 2022). "Moreover, both FAK and MYO1E have been found to promote mammary tumor progression." (PMID 32272642, 2020). "More recently, a meta-analysis of human data has shown a correlation between high MYO1E expression and poor prognosis in BLBC and grade-1 breast cancer." (PMID 32272642, 2020). "Immunostaining of tumors identified expression of MYO1E in the mammary tumors from MYO1E WT PyMT mice, where it was enriched at cell-cell junctions, and no MYO1E signal in the MYO1E KO PyMT mice (data not shown)." (PMID 27329840, 2016).
breast carcinoma (continued). "While MYO1E KO mice display no apparent changes in the mammary gland development, MMTV-PyMT mice deficient in MYO1E exhibit delayed mammary tumor formation and decreased tumor number." (PMID 27329840, 2016). "Furthermore, in a breast cancer murine model, mice lacking MYO1E had tumors with increased differentiation and reduced proliferation." (PMID 36914720, 2023).
focal segmental glomerulosclerosis (8 papers, 2013 to 2026). A renal disorder characterized by sclerotic lesions in the glomeruli. "Biallelic variants in MYO1E, encoding the class I myosin Myo1E, cause a distinctive form of focal segmental glomerulosclerosis (FSGS) often accompanied by "Alport-like" multilamination of the glomerular basement membrane (GBM)." (PMID 41898697, 2026). "MYO1E mutations are associated with focal segmental glomerulosclerosis, characterized by an increased risk of CVD, primary due to increase in dyslipidemia and hypertension." (PMID 39187864, 2024). "A missense mutation in MYO1E causes focal segmental glomerulosclerosis and a homozygous truncation mutation in the motor domain of MYO1E has been linked to nephrotic syndrome, both childhood—onset forms of kidney disease." (PMID 36551317, 2022). "Point mutations in the human MYO1E gene, encoding class I myosin Myo1e, are associated with focal segmental glomerulosclerosis (FSGS), a primary kidney disorder that leads to end-stage kidney disease." (PMID 26092123, 2015). "MYO1E biallelic, generally missense, mutations have been reported in children with focal segmental glomerulosclerosis and glucocorticoid-resistant proteinuria." (PMID 25739341, 2015). "Complete knockout of Myo1e in mice and MYO1E mutations (A159P and Y695X) in humans are associated with nephrotic syndrome and focal segmental glomerulosclerosis." (PMID 23977349, 2013). "Mutations in the MYO1E gene in humans are associated with focal segmental glomerulosclerosis (FSGS), a kidney disease arising from the disruption of the protein filtration barrier in the kidney, which leads to proteinuria (protein excretion in the urine)." (PMID 26092123, 2015). "MYO1E is a gene implicated in focal segmental glomerulosclerosis and it encodes a podocyte-expressed non-muscle myosin." (PMID 25739341, 2015). "The behavior of the abnormal Myo1e protein also provides a hint as to why agents that stabilize the podocyte cytoskeleton (e.g., cyclosporine) are important to the successful therapy of focal segmental glomerulosclerosis." (PMID 23977349, 2013).
nephrotic syndrome (7 papers, 2013 to 2025). A collection of symptoms that include severe edema, proteinuria, and hypoalbuminemia; it is indicative of renal dysfunction. "Those who had concomitant COL4A5 and MYO1E mutations presented with nephrotic syndrome and rapidly progressed to ESKD, in contrast to those that only harbored the COL4A5 variant." (PMID 40003707, 2025). "Myosin-1E is of particular interest as mutations in MYO1E cause nephrotic syndrome and it has also been implicated as a genetic modifier in Alport syndrome." (PMID 32147508, 2020). "Additional variants in endocytosis proteins important for SD maintenance and function have been associated with nephrotic syndrome in patients, including variants in Myosin-1E (Myo1E; binds Dynamin and Synaptojanin), and CD2AP (a major binding partner of Endophilin)." (PMID 35265622, 2022). "Mutations in the protein coding paired box gene 2 (PAX2) and in the non-muscle class I myosin, myosin 1E, (MYO1E) have been implicated in the development of steroid-resistant nephrotic syndrome." (PMID 35574290, 2022).
Nephropathy (4 papers, 2015 to 2026). A nonspecific term referring to disease or damage of the kidneys. "As described in this paper, the screening for MYO1E or other non-COL4 podocyte gene mutations in XLAS is suggested when clinical nephropathy is more severe than expected." (PMID 29089023, 2017). "This case broadens clinicopathologic recognition of MYO1E-associated nephropathy and highlights the teaching point that Alport-like GBM changes are not pathognomonic for type IV collagen disorders but may signal defects in podocyte cytoskeletal anchoring." (PMID 41898697, 2026). "We suggest screening for MYO1E and other non-COL4 ‘podocyte gene’ mutations in XLAS when clinical nephropathy is more severe than expected for an individual’s age and sex." (PMID 25739341, 2015). "Furthermore, the study suggests that coinheritance of COL4A5 and MYO1E variants predicts an increased severity of kidney diseases, and a novel COL4A5 c.3097G>C variant was identified together with MYO1E variants in a patient with presumed nephropathy and no confirmed diagnosis." (PMID 41300747, 2025).
Alport syndrome (2 papers, 2016 to 2020). A rare renal disease characterized by glomerular nephropathy with hematuria progressing to end-stage renal disease (ESRD), frequently associated with sensorineural deafness, and occasionally with ocular anomalies. "We employed serial block face-scanning electron microscopy to investigate Alport syndrome, the commonest monogenic glomerular disease, and compared findings to other genetic mouse models of glomerular disease (Myo1e−/−, Ptpro−/−)." (PMID 27725732, 2016). "Podocyte invasions occurred in Alport (Col4a3−/−), Myo1e−/− and Ptpro−/− mice and lucent regions of GBM, resembling sites of podocyte invasion, were seen in patients with Alport syndrome." (PMID 27725732, 2016).
autism (2 papers, 2016 to 2020). Persistent deficits in social interaction and communication and interaction as well as a markedly restricted repertoire of activity and interest as well as repetitive patterns of behavior. "Another sequencing study found mutations within the putatively regulatory regions of the MYO1E gene in autism-affected probands." (PMID 27562213, 2016). "We analyzed the Simons Simplex Collection of 2508 parent-offspring autism trios using VARPRISM, replicating 44 genes previously implicated in autism susceptibility and identifying 20 additional candidate genes, including MYO1E, KCND3, PDCD1, DLX3, and TSPAN4 (false discovery rate < 0.3)." (PMID 27562213, 2016).
autosomal recessive steroid-resistant nephrotic syndrome (2 papers, 2013 to 2025). "Mutations or dysregulation of MYO1E can lead to kidney diseases, such as autosomal recessive steroid-resistant nephrotic syndrome (SRNS), which disrupts the protein’s function, leading to podocyte injury and proteinuria." (PMID 41368354, 2025).
breast tumor (2 papers, 2016 to 2018). "Investigation of gene expression signatures in basal-like breast tumors showed a correlation between MYO1E mRNA expression level and poor prognosis." (PMID 29934580, 2018). "Overall, our data suggests that MYO1E contributes to breast tumor malignancy and regulates the differentiation and proliferation state of breast tumor cells." (PMID 27329840, 2016). "Considering elevated level of MYO1E expression in breast tumors and our data identifying MYO1E as a novel regulator of tumor progression, MYO1E may be useful as a target for development of specific inhibitors that would interfere with tumor progression and invasion." (PMID 27329840, 2016). "The molecular mechanisms that result in papillary tumor formation have not been identified, however our findings suggest that the presence or absence of MYO1E can direct breast tumor development towards either solid or papillary morphology, respectively." (PMID 27329840, 2016).
glomerular disease (2 papers, 2013 to 2016). "Meanwhile, renal tissue from Myo1e-null mice demonstrated changes characteristic of glomerular disease including a thickened and disorganized glomerular basement membrane and flattened podocyte foot processes." (PMID 23977349, 2013).
lung adenocarcinoma (2 papers, 2023 to 2024). A carcinoma that arises from the lung and is characterized by the presence of malignant glandular epithelial cells. "Furthermore, other members of the class I myosin family, such as MYO1B and MYO1E, have been associated with poorer survival outcomes in colorectal cancer and lung adenocarcinoma, respectively." (PMID 39205690, 2024).
lung carcinoma (2 papers, 2020 to 2023). "This study suggests that changes in MYO1E methylation and expression in LUAD patients may have an essential role in lung cancer’s pathogenesis." (PMID 36914720, 2023).
renal failure (2 papers, 2016). "Myo1e−/− mice develop FSGS and renal failure associated with morphological abnormalities in both podocytes and the GBM; we therefore investigated adult Myo1e−/− mouse glomeruli with SBF-SEM." (PMID 27725732, 2016).
congenital nephrotic syndrome (1 paper, 2013). "In addition to foot process staining, Myo1e exhibited prominent mesangial region staining, which was more evident in kidney sections from patients with congenital nephrotic syndrome of the Finnish type (CNF)." (PMID 23977349, 2013).
cyst (1 paper, 2013). A sac-like closed membranous structure that may be empty or contain fluid or amorphous material. "Finally, the MYO1E knock-down resulted in pericardial edema, an expanded Bowman’s space, and pronephric cyst phenotypes, consistent with the inability to osmoregulate." (PMID 23977349, 2013).
hepatocellular carcinoma (1 paper, 2015). A malignant tumor that arises from hepatocytes. "Increased levels of MYO1E mRNA have been associated with recurrence of hepatocellular carcinoma." (PMID 26444668, 2015).
keloid (1 paper, 2019). An irregularly shaped, elevated mark on the skin caused by deposits of excessive amounts of collagen during wound healing. "Elevated TGF-β signaling and the Myo1e activity are closely associated with similar pathological outcomes, such as tumorigenesis, keloid, and tissue fibrosis." (PMID 31408934, 2019). "Moreover, genome-wide association studies have shown that Myo1e single-nucleotide polymorphisms are associated with keloid formation (i.e., a wound healing reaction with excessive scar formation)." (PMID 31408934, 2019).
liver cancer (1 paper, 2025). An epithelial or non-epithelial malignant neoplasm that arises from the liver. "The analysis of TCGA liver cancer data showed that the expressions of AGFG1, IQGAP3, SPINK1, CXCL9, MYO1E, and POF1B were significantly increased in tumor tissues." (PMID 41578779, 2025).
melanoma (1 paper, 2020). A malignant, usually aggressive tumor composed of atypical, neoplastic melanocytes. "This MYO1E–FAK interaction has been reported previously in melanoma, which we discuss in the next section." (PMID 32272642, 2020). "FAK and MYO1E interaction can be involved in the molecular basis of tumoral processes associated with FAK-dependent activity, such as melanoma." (PMID 32272642, 2020).
non-small cell lung carcinoma (1 paper, 2023). A group of at least three distinct histological types of lung cancer, including non-small cell squamous cell carcinoma, adenocarcinoma, and large cell carcinoma. "This study aims to perform a comprehensive genomic analysis to assess the influence of overexpression of MYO1E in non-small cell lung carcinoma (NSCLC) and whether there are differences in survival and mortality risk in NSCLC patients depending on both DNA methylation and RNA expression of MYO1E." (PMID 36914720, 2023).
pancreatic cancer (1 paper, 2024). "This study identifies and validates a novel five-gene transcriptomic signature (LAMC2, TSPAN1, MYO1E, MYOF, and SULF1) as both diagnostic biomarkers and potential drug targets for pancreatic cancer." (PMID 39850570, 2024).
sarcoma (1 paper, 2011). A usually aggressive malignant neoplasm of the soft tissue or bone. "Indeed we found increased expression levels for RMS-markers (Myog, Myl4, Igf2, Prox1), a FS-gene (Vcan), and LS-related genes (Pparg, Myo1e, Hoxa5, Plau), which further established the MD-tumors as mixed sarcomas consisting of RMS, FS and LS-compartments." (PMID 21533183, 2011).
squamous cell carcinoma (1 paper, 2024). A carcinoma arising from squamous epithelial cells. "In this work, our screening uncovered previously unidentified prognostic gene expression indicators, namely, MYO1E, FAM83 homologs, and DKK1 for adenocarcinoma, and FGA and TRIB1 for squamous cell carcinoma." (PMID 39513892, 2024).